PRMT1 (protein arginine methyltransferase 1)
Description:
Arginine methyltransferase that methylates (mono and asymmetric dimethylation) the guanidino nitrogens of arginyl residues present in proteins such as ESR1, histone H2, H3 and H4, FMR1, ILF3, HNRNPA1, HNRNPD, NFATC2IP, SUPT5H, TAF15, EWS, HABP4, SERBP1, RBM15, FOXO1, CHTOP, MAP3K5/ASK1, MICU1 and NPRL2. Constitutes the main enzyme that mediates monomethylation and asymmetric dimethylation of histone H4 'Arg-3' (H4R3me1 and H4R3me2a, respectively), a specific tag for epigenetic transcriptional activation. May be involved in the regulation of TAF15 transcriptional activity, act as an activator of estrogen receptor (ER)-mediated transactivation, play a key role in neurite outgrowth and act as a negative regulator of megakaryocytic differentiation, by modulating p38 MAPK pathway. Methylates RBM15, promoting ubiquitination and degradation of RBM15. Methylates MRE11 and TP53BP1, promoting the DNA damage response. Methylates FOXO1 and retains it in the nucleus increasing its transcriptional activity. Methylates CHTOP and this methylation is critical for its 5-hydroxymethylcytosine (5hmC)-binding activity. Methylates MAP3K5/ASK1 at 'Arg-78' and 'Arg-80' which promotes association of MAP3K5 with thioredoxin and negatively regulates MAP3K5 association with TRAF2, inhibiting MAP3K5 stimulation and MAP3K5-induced activation of JNK. Methylates H4R3 in genes involved in glioblastomagenesis in a CHTOP- and/or TET1-dependent manner. Plays a role in regulating alternative splicing in the heart (By similarity). Methylates NPRL2 at 'Arg-78' leading to inhibition of its GTPase activator activity and then the GATOR1 complex and consequently inducing timely mTORC1 activation under methionine-sufficient conditions. Methylates the C-terminus of DSP, promoting its phosphorylation by GSK3B and subsequent recruitment to desmosome cell-cell junctions.
Synonyms: HRMT1L2; IR1B4; HCP1; ANM1
Tractability: Small molecule: a structure with a bound ligand is known; a high-quality ligand is known. PROTAC: UniProt records ubiquitination sites on it; ubiquitination databases record sites on it; its protein half-life has been measured; a small molecule that binds it is known.
Target class: Epigenetic regulator; Protein arginine methyltransferase; Writer; Protein methyltransferase
Chemical probes: MS023 (high quality)
Gene: Protein-coding gene on chromosome 19 (49,675,786 to 49,689,029, forward strand). Ensembl gene ENSG00000126457.
Subcellular location: Nucleus; Nucleus, nucleoplasm; Cytoplasm; Cytoplasm, cytosol; Lysosome membrane
Subcellular location (Human Protein Atlas): Nucleoplasm
Pathways (Reactome):
Gene expression (Transcription): RUNX1 regulates genes involved in megakaryocyte differentiation and platelet function
Signal Transduction: Estrogen-dependent gene expression; Extra-nuclear estrogen signaling
Chromatin organization: RMTs methylate histone arginines
Disease: Maturation of nucleoprotein
Gene Ontology:
Molecular function: arginine N-methyltransferase activity; enzyme binding; histone H4R3 methyltransferase activity; histone methyltransferase activity; identical protein binding; methyl-CpG binding; methyltransferase activity; mitogen-activated protein kinase p38 binding; N-methyltransferase activity; protein binding; protein methyltransferase activity; protein-arginine N-methyltransferase activity; protein-arginine omega-N asymmetric methyltransferase activity; protein-arginine omega-N monomethyltransferase activity; RNA binding; S-adenosyl-L-methionine binding; GATOR1 complex binding; histone H4 methyltransferase activity
Biological process: cellular response to methionine; DNA damage response; negative regulation of apoptotic process; negative regulation of JNK cascade; negative regulation of megakaryocyte differentiation; neuron projection development; positive regulation of double-strand break repair via homologous recombination; positive regulation of erythrocyte differentiation; positive regulation of TORC1 signaling; positive regulation of translation; regulation of BMP signaling pathway; regulation of megakaryocyte differentiation; cardiac muscle tissue development; cell surface receptor signaling pathway; positive regulation of hemoglobin biosynthetic process; positive regulation of p38MAPK cascade; RNA splicing; viral protein processing; chromatin remodeling; protein homooligomerization
Cellular component: cytoplasm; lysosomal membrane; methylosome; nucleoplasm; nucleus; cytosol
Genetic constraint (gnomAD): Loss-of-function variants: 5 observed, 48.15 expected, observed/expected ratio (o/e) 0.1, 90% interval 0.053 to 0.22. The upper end of that interval is the gene's LOEUF score, 0.22, which puts it in group 1 of 6, group 1 being the genes least tolerant of losing a copy. Missense variants: 249 observed, 527.7 expected, observed/expected ratio (o/e) 0.47, 90% interval 0.43 to 0.52. Synonymous variants: 227 observed, 207.95 expected, observed/expected ratio (o/e) 1.09, 90% interval 0.98 to 1.22.
Homologues: Orthologues: chimpanzee PRMT1 (100% identical), dog PRMT1 (100% identical), guinea pig PRMT1 (100% identical), macaque PRMT1 (100% identical), mouse Prmt1 (99% identical), rat Prmt1 (99% identical), rabbit PRMT1 (99% identical), pig PRMT1 (94% identical), tropical clawed frog prmt1 (92% identical), zebrafish prmt1 (83% identical), Drosophila melanogaster Art2 (38% identical). Paralogues in human: PRMT8 (77% identical), PRMT3 (45% identical), CARM1 (33% identical), PRMT6 (31% identical), PRMT2 (30% identical), PRMT9 (23% identical), PRMT7 (20% identical).
Diseases named in the same sentence as PRMT1 in open-access papers:
PRMT1 is named in the same sentence as 190 diseases in open-access papers, as found by Europe PMC text mining. Sharing a sentence is not in itself a finding about the gene and the disease. The quoted sentences say what the papers report.
breast carcinoma (79 papers, 2008 to 2025). "Suppression of PRMT1 using an siRNA can attenuate proliferation and migration of breast cancer cells and is predicted to cause longer survival of breast cancer patients." (PMID 40001488, 2025). "Several studies have reported that high PRMT1 expression is associated with prognosis in gastric and breast cancers." (PMID 41476984, 2025). "This deviant estrogen signal transduction seen in breast cancer can be the cause of ERα hypermethylation by PRMT1, resulting in cytoplasmic localization of the ERα and subsequent cancer progression." (PMID 40001488, 2025). "PRMT1 is implicated in numerous oncogenic pathways, including transcriptional regulation, DNA repair, and cell signaling, promoting breast cancer cell proliferation, invasion, and resistance to therapy." (PMID 39201539, 2024). "The gene with the highest MS was ZNF676, which is closely associated with the PRMT1 gene that is involved in breast cancer metastasis." (PMID 37761960, 2023). "In particular, circRNAs deriving from genes that are already established risk factors in breast cancer, such as PRMT1, constitute highly promising targets for transcriptomics studies." (PMID 35885916, 2022). "We further analyzed the mRNA levels of PRMT1 and c-Myc regulatory genes and their associations with olaparib sensitivity in breast cancer cells by using the CCLE database." (PMID 34683150, 2021). "Increased expression of PRMT1 has been implicated in the tumorigenesis of multiple cancers including progesterone receptor positive breast cancer, hepatocellular carcinoma (HCC), neuroblastoma, and pancreatic cancer." (PMID 33440687, 2021). "The log rank test analyses revealed that the increased PRMT1 mRNA was significantly negatively associated with DSS of the patients with breast cancer." (PMID 34440533, 2021). "The results presented herein demonstrate that breast cancer cells with elevated PRMT1 were closely associated with the therapeutic efficacy of olaparib." (PMID 34683150, 2021). "ERα is an important PRMT1 substrate whose methylation can be associated with the development of breast cancer." (PMID 34833023, 2021). "Herein, we identified that breast cancer cells with an elevated expression of protein arginine methyl transferase 1 (PRMT1) was associated with therapeutic sensitivity to the PARP inhibitor olaparib." (PMID 34683150, 2021). "For example, overexpression of protein arginine methyltransferase 1 (PRMT1) has been associated with the methylation of the transcription factor C/EBPα and inhibition of its tumor suppressor function in breast cancer." (PMID 32873298, 2020). "Loss of PRMT1 in aggressive breast cancer cells strongly blocks tumour metastasis in vivo, and inhibits breast cancer cells proliferation by inducing cellular senescence." (PMID 26813495, 2016). "CARM1 is an essential part of the estrogen-stimulated breast cancer growth downstream of ERα and its aberrant expression as well as PRMT1 overexpression is linked to breast cancer." (PMID 21814622, 2011). "Intriguingly, the correlations of olaparib sensitivities with transcriptome-wide mRNA expression in breast cancer cell lines revealed that the PRMT1 gene was within the top ranks, and breast cancer cells with an elevated expression of PRMT1 were associated with therapeutic resistance to olaparib." (PMID 34683150, 2021). "Breast cancer patients expressing high levels of PRMT1 but low levels of USP11 are associated with a poor survival rate, which could be a consequence of defective end-resection thereby favouring error-prone NHEJ and genome instability." (PMID 34728620, 2021). "Indeed, the expression levels of PRMT1 and the methylation levels of the Arg342 residue of EZH2 correlate with poor clinical outcomes in breast cancer patients, suggesting the utility of PRMT1 as a diagnostic marker and therapeutic target for cancer." (PMID 34006904, 2021).
breast carcinoma (continued). "However, breast cancer cells that exhibited resistance to olaparib were closely associated with PRMT1 or the MYC-targeted signature, specifically in TNBC cell lines." (PMID 34683150, 2021). "We observed that PRMT1 depletion or treatments designed to prevent SAM or ATP accumulation in breast cancer cells made the cells more susceptible to IR-induced apoptosis both in vitro and in vivo, while PRMT1 overexpression protected MDA-MB-231 cells from apoptosis at high IR doses." (PMID 32764667, 2020). "Since the NHEJ-promoting function of 53BP1 is inhibited by BRCA1, loss of BRCA1 at DSBs in PRMT1-silenced breast cancer cells may suppress HR and direct DNA repair toward NHEJ." (PMID 32764667, 2020). "In addition, a loss-of-function study in a breast cancer cell line MDA-MB-231 that expresses PRMT1 at a detectable level was performed." (PMID 26813495, 2016). "Similarly, a recent study has demonstrated that the expression of one of the splice variants of PRMT1 is highly associated with colon cancer and breast cancer." (PMID 23977297, 2013). "Similarly, the presence of PRMT1-v1 seems to be associated with clinical and pathological features and poor prognosis in breast cancer patients (our unpublished data)." (PMID 19078953, 2008). "Notably, PRMT1—a gene linked to cell cycle regulation—was consistently overexpressed across all samples, suggesting an important role in both metastasis and chemoresistance in breast cancer." (PMID 40927753, 2025). "In breast cancer, PRMT1 modifies C/EBPα and EZH2 to activate Cyclin D1 while repressing p16 and p21, accelerating G1/S progression." (PMID 41204384, 2025). "Data from TCGA were utilized to examine the differential expression of PRMT1 across various breast cancer tissue types and adjacent normal breast tissues." (PMID 40927753, 2025). "In breast cancer, PRMT1 isoforms, particularly PRMT1-v1, are differentially expressed; however, the functional consequences and prognostic value of specific variants have yet to be fully characterized." (PMID 40791817, 2025). "Using The Cancer Genome Atlas (TCGA) for pan-cancer analysis, we found that PRMT1 expression is significantly higher in breast cancer tumors than in normal tissue." (PMID 40927753, 2025). "Previous research conducted by our research team has demonstrated that PRMT1 can enhance the proliferation of breast cancer cells by inhibiting the transcription and expression of p16 and p21." (PMID 39890802, 2025). "PRMT1’s ability to influence oncogenic pathways makes it a key target for cancer treatments, especially in breast cancer, where it affects metastasis and drug resistance." (PMID 40927753, 2025). "Meanwhile, the knockdown of PRMT1 not only suppressed metastasis in vivo in mice but also provoked cellular senescence in breast cancer cells." (PMID 41154773, 2025). "PRMT1 can methylate the estrogen receptor ERα within the DNA-binding domain, thereby regulating the ER signaling pathway to promote breast cancer cell proliferation." (PMID 41154773, 2025). "Previous studies conducted by our research team have revealed that PRMT1 plays a role in promoting the proliferation and metastasis of both breast cancer and colorectal cancer." (PMID 39890802, 2025). "Immunohistochemical staining revealed increased PRMT1 expression in breast cancer tissues compared to normal tissue, with even higher levels in lung metastases than in primary tumors." (PMID 40927753, 2025). "PRMT1 is crucial for breast cancer’s metastasis and chemoresistance, with its expression level closely linked to patient outcomes." (PMID 40927753, 2025). "In breast cancer, PRMT1 promotes EMT by activating ZEB1 transcription via H4R3me2a modification, whereas PRMT1 silencing induces G1 arrest and cellular senescence." (PMID 41204384, 2025).
breast carcinoma (continued). "In breast cancer, PRMT1 methylates the RNA helicase DDX3, stabilizing the protein and facilitating its mitochondrial translocation, where, under stress conditions, DDX3 promotes PINK1 translation to drive CSC-like traits and metastatic progression." (PMID 41204384, 2025). "In breast cancer, PRMT1 promotes ZEB1 transcription via H4R3me2a, facilitating cell migration and invasion." (PMID 41204384, 2025). "A LASSO Cox regression model incorporating PRMT1, PARP1, P65, and IL-1B indicates that these molecules are linked to poor prognosis in breast cancer, confirmed by the GSE6532 dataset." (PMID 40927753, 2025). "Overexpression of PRMT1 has been detected in all breast cancer subtypes in comparison to healthy breast tissue, although it does not always affect the estrogen or progesterone hormone signaling cascades." (PMID 40001488, 2025). "For example, PRMT1 overexpression is associated with increased arginine methylation and aberrant exon inclusion of SRSF1, which is essential for breast cancer cell growth; PRMT1 suppresses the anti-tumor immune response via arginine methylation of cGAS." (PMID 40744915, 2025). "Their intricacy in structure and distinct expression profiles among breast cancer cells raises new questions about the functions of circRNAs and the regulatory role of PRMT1 in breast cancer." (PMID 37692475, 2024). "Radiation-induced damage to breast cancer cells increases levels of S-Adenosyl methionine and enhances PRMT1 enzymatic activity, leading to the methylation of BRCA1." (PMID 38326807, 2024). "In conclusion, recent insights into the multifaceted role of PRMT1 in breast cancer underscore the need for further investigation, positioning PRMT1 as a promising therapeutic target in breast cancer treatment." (PMID 38326807, 2024). "More interestingly, the MCF-12A cell line, which originates from normal breast epithelium, characteristically differs from the breast cancer cell lines regarding the exon extensions that are incorporated in its PRMT1 circRNAs." (PMID 37692475, 2024). "Recent research has demonstrated heightened PRMT1 expression in breast cancer specimens compared to normal tissues, establishing a correlation between elevated PRMT1 levels and malignancy in breast cancer patients." (PMID 38326807, 2024). "In breast cancer cells, PRMT1 plays a crucial role in mediating the asymmetric dimethylation of histone H4 at arginine 3 within the ZEB1 promoter, facilitating the transcriptional expression of ZEB1, a key factor in the EMT process." (PMID 38326807, 2024). "For this reason, the expression levels of the novel PRMT1 circRNAs as well as their secondary structure and cellular topology are aspects necessitating future investigation, to elucidate their role in breast cancer." (PMID 37692475, 2024). "In breast tumors, PRMT1 overexpression is associated with increased SRSF1 arginine methylation and aberrant exon inclusion, which are critical for breast cancer cell growth in vivo and in vitro." (PMID 39201539, 2024). "Through analyzing the role of PRMT1 in tumorigenesis and immune cell infiltration for patients in TCGA, we found PRMT1 was highly expressed in most cancer types, including breast cancer (BRCA)." (PMID 37193698, 2023). "Aberrant expression of PRMT1 has been reported to be involved in tumorigenesis and is an unfavorable prognostic biomarker in breast cancer and colorectal cancer." (PMID 36669591, 2023).